TFF3 (trefoil factor 3)
Diseases named in the same sentence as TFF3 in open-access papers (continued):
Sharing a sentence is not in itself a finding about the gene and the disease.
cancer (continued). "The PC2 cluster showed high expression in TFF3 and REG4, where cells were obtained from the cancer tissue of intestinal patients." (PMID 35087207, 2022). "Several inflammatory cytokines, such as CD31, BDNF, TFF3, Serpin E-1, VCAM-1, Vitamin D BP, and PDGF-AA, were significantly upregulated in cancer survivors while MMP9 and Osteopontin both had significant positive correlations with barriers to care." (PMID 32587352, 2020). "Forced expression of TFF3 in CMS4 CRC cells promoted cell proliferation, cell survival, foci formation, invasion, migration, cancer stem cell like behaviour and growth in 3D Matrigel." (PMID 31835445, 2019). "Forced expression of TFF3 in lung ADC cells enhanced cell proliferation and survival, increased anchorage-independent growth, cancer stem cell behavior, growth in 3D Matrigel, and cell migration and invasion." (PMID 31685806, 2019). "Known PCa-related genes (SPON2, TFF3, SPINK1) are among the highest-expressed genes in the “cancer” factor." (PMID 29925878, 2018). "However, since a previous modeling study suggested that the Cytosponge-TFF3 test combined with endotherapy for treating early cancer had cost advantages over endoscopy, this approach may open up the possibility for more systematic diagnosis of a broader subgroup of the population in the future." (PMID 25634542, 2015). "Selected targets were confirmed by immunohistochemistry: NPY and PLA2G7 (up-regulated in ERG+ cancers), and AZGP1 and TFF3 (down-regulated in ERG+ cancers)." (PMID 23390522, 2013). "Among these proteins, trefoil factor 3 (TFF3) was increased in the EGC group compared with that in the IM/ATP group, which is involved in multiple aspects of cancer progression and has been reported to be increased in serum samples from patients with GC and more severe IM stages." (PMID 38584705, 2024). "Whereas TFF3 has been suggested to exert pivotal functions in the development and progression of multiple cancers, the functions of TFF3 in PDAC have not been reported." (PMID 35332126, 2022). "For example, the use of siRNA to silence TFF3 in cancer cells inhibited of MAPK/ERK signaling pathway, leading to a significant decrease in cell survival, whereas exogenous administration of TFF3 significantly activated the ERK pathway and promoted cancer-cell invasion." (PMID 35039476, 2022). "Heatmap analysis of the top differentially expressed genes (DEGs) delineated the signatures of each cell type among the six positive lymph nodes, with cancer cells highly expressing genes includingTFF1,AGR2,TFF3, and myeloid cells highly expressing genes includingC1QB,RNASE1 andAPOE." (PMID 36148946, 2022). "We discovered that serum TFF3, Romo-1 and NF-кB levels were significantly higher in patients with EC or OC compared to those without cancer instead of serum SFRP4 levels that were significantly lower in cancer groups compared to the control one." (PMID 35461390, 2022). "Serum TFF-3, Romo-1 and NF-кB levels were significantly higher in patients with EC and OC than those without cancer." (PMID 35461390, 2022). "It has been reported that the WNT pathway promotes cancer stem cell (CSC)-like behavior in multiple cancers, and hence it was next determined whether TFF3 regulates CSC-like behavior in PDAC." (PMID 35332126, 2022). "The DMRs identified when comparing LowHR HRpos-like samples and TNBCs included cancer-relevant genes such as EN1, TFF3 or IRX1 which have previously been described to be differentially methylated and expressed in TNBCs and hormone receptor positive breast cancers." (PMID 34602069, 2021). "To provide further evidence, we isolated primary carcinoma cells from two human CRC specimens and found that TFF3 induced PTGS2 expression in a dose-dependent manner, which could be blocked by niclosamide." (PMID 34262017, 2021). "Furthermore, forced expression of TFF3 decreased doxorubicin sensitivity of HCC cells, which was attributed to increased doxorubicin efflux and cancer stem cell-like behavior of Hep3B cells." (PMID 28445151, 2017).
cancer (continued). "Additionally, TFF3 gene expression was positively associated with the AUC values of chemotherapy drugs in the Genomics of Drug Sensitivity in Cancer version 1‌ (GDSC1) database, indicating that higher TFF3 expression corresponds to lower chemotherapy sensitivity." (PMID 41551914, 2026). "Importantly, only 6 (13.0%) cancers were stained by TFF1 weaker than surrounding non-cancerous epithelial tissue, and only 4 (8.7%) cancers was stained for TFF3 weaker than surrounding non-cancerous epithelial tissue." (PMID 28687783, 2017). "In conclusion, we have demonstrated highly significant and frequent cancer-specific promoter hypomethylation of TFF3 in malignant compared to non-malignant prostate tissue samples in two large independent RP cohorts, including a total of 789 PC and 94 NM tissue samples." (PMID 28930171, 2017). "Important cancer related genes identified for this phenotype are CDK6 gene, which inhibits proliferation of human mammary epithelial cells; SIAT4C, which is down-regulated in RCC, RHOB, which is known to be a pro-apoptotic and tumor suppressor gene, and the FLT1 and TFF3 gene." (PMID 19458770, 2007). "Among those who were offered the Cytosponge-TFF3 procedure but did not have the test (n=5084), one participant, who initially expressed interest in the procedure, but was referred for an endoscopy before it could be done, was diagnosed with early-stage cancer." (PMID 32738955, 2020). "Not surprisingly, similarity among different cancer types was identified in only 6 out of 23 clusters, including E3 (IRS2, KRT6A), E5 (CD24, STMN1), E8 (GKN1, MUC5AC), E9 (PHGR1, TFF3), E10 (TFF3, TPO) and E13 (VTN and ITIH5)." (PMID 36333338, 2022). "TFF3 is an intestinal marker not expressed normally in the upper GI tract, but is strongly expressed in both BE and GIM, and its expression also decreases during cancer development." (PMID 36994101, 2023). "Immunofluorescent staining of primary CRC sections with antibodies directed against the stem cell marker OLFM4, the proliferation marker KI67, and the differentiation markers TFF3 and FABP1 revealed cell heterogeneity, but not how cancer cells in the tissue are related to each other (Fig EV4)." (PMID 34409732, 2021). "There is an argument that screening for TFF3 as a surrogate for IM may be limited by the reduction in goblet cells as BO progresses to cancer, however, our BEST2 trial showed that the sensitivity for TFF3 in the presence of dysplasia is not reduced by dysplastic grade." (PMID 35843173, 2022).
infection (23 papers, 2011 to 2025). The state of being infected such as from the introduction of a foreign agent such as serum, vaccine, antigenic substance or organism. "There was a strong association of age with serum levels of TFF2 and TFF3, and but the sample size within the infected and uninfected age groups restricted a formal analysis of age and infection interaction." (PMID 34662329, 2021). "Based on our analysis, anti-correlated expression of miR-125a-5p and miR-615-3p was associated with the dysregulation of MUC2 and TFF3 transcription at the early stage of C. jejuni NCTC 11168 infection in vitro." (PMID 34183045, 2021). "As we previously reported, Ki-67 and CD44v expression were elevated in mice with PMSS1 infection compared to mock-infected mice, whereas TFF3 expression was decreased." (PMID 36598261, 2023). "In order to address this and find associated regulatory networks in response to C. jejuni infection, we determined the transcription of MUC2 and TFF3 in the human intestinal epithelial cell line HT-29/B6 following C. jejuni NCTC 11168 infection." (PMID 34183045, 2021). "Upon infection, the transcript level of TFF3 showed an early peak followed by a 0.61-fold decline at 5 h p.i. and a return to control levels until 24 h p.i.." (PMID 34183045, 2021). "Here, we observed significantly increased transcription of both MUC2 and TFF3 in cells derived from human colonic epithelial cell line HT-29/B6 immediately after C. jejuni NCTC 11168 infection." (PMID 34183045, 2021). "C. jejuni 81–176 infection resulted in a pronounced decrease of TFF3 transcription when compared to naïve controls (0.38-fold change, P ≤ 0.0001), whereas the MUC2 transcription was slightly decreased upon infection (0.80-fold change, P ≤ 0.05)." (PMID 34183045, 2021). "The relative fold differences of MUC2 and TFF3 mRNA levels were calculated and revealed an approximately 2-fold up-regulation (P ≤ 0.01) of both factors relatively early (i.e., 1 h) post infection (p.i.)." (PMID 34183045, 2021). "An inverse correlation between two predicted miRNAs and MUC2 as well as TFF3 was observed in the early phase of C. jejuni NCTC 11168 infection in human cells." (PMID 34183045, 2021). "TFF3, involved in wound healing, mucosal protection, cell proliferation and cell migration, was strongly upregulated (21.54-fold) by infection in the R line of the HSF flock when compared to its S counterparts." (PMID 30678719, 2019). "It is therefore, feasible that the observed up-regulation of TFF3 is a response to IL-4 and IL-13 production or mucosal damage following infection." (PMID 21385411, 2011). "TFF3 was also found to be significantly upregulated in the small intestine of sheep infected with Trichostrongylus columbriformis and in rats during infection with N. brasiliensis." (PMID 21569362, 2011). "In contrast, infection with Citrobacter rodentium alone reduces TFF3 expression and RagKO (T and B cell-deficient) mice did not exhibit this reduction." (PMID 34066339, 2021). "Likewise, we observed anti-correlated transcription of miR-615-3p with MUC2 and TFF3 mRNA upon established C. jejuni 81-176 infection in vivo." (PMID 34183045, 2021). "Therefore, the relative transcription of MUC2 and TFF3 was measured in colonic tissue samples taken at day 6 following peroral infection of secondary abiotic IL-10−/− mice." (PMID 34183045, 2021). "Furthermore, in rodent models, TFF3 expression is increased in the colon after infection with pathogens, such as Nippostrongylus brasiliensis, Bifidobacterium dentium, and co-infection with Giardia muris and Citrobacter rodentium." (PMID 34066339, 2021). "Tff3 mRNA jejunal transcripts peaked between 5–7d post infection." (PMID 31562318, 2019).
infection (continued). "We observed that butyrate-treated mice challenged with C. rodentium showed differing increases in gene expression of cytokines involved in the clearance of infection (Il17A, Tnfα), the reduction of mucosal inflammation (Tgfβ, Il10), and the improvement of host barrier function (Muc2, Relmβ, Tff3)." (PMID 28861518, 2017). "Indeed,the predictive power of the HP infection status was less than that of either serum TFF3 or the PG test." (PMID 24720760, 2014). "Therefore, we assume that the observed dysregulation of MUC2 and TFF3 upon in vitro and in vivo C. jejuni infection was associated to the stage of infection rather than to the strains." (PMID 34183045, 2021). "Our study revealed that morbillivirus triggers massive upregulation of TFF1, TFF3 and, to a lesser degree, TFF2 expression, provided infection occurred during lung immune homeostasis." (PMID 38331906, 2024). "Firstly, we confirmed that C. jejuni NCTC 11168 infection induced an altered transcription of MUC2 and the co-secreted peptide TFF3 in human intestinal epithelial cells in vitro." (PMID 34183045, 2021). "In contrast, infection with the blood fluke S. haematobium decreased TFF2 and TFF3 levels in serum of infected Nigerian children, also with some evidence of age-dependence." (PMID 34662329, 2021). "In colonic tissue samples, we confirmed infection-dependent aberrant transcription of MUC2 and TFF3." (PMID 34183045, 2021). "Regarding the other two members of the family, we measured an up-regulation (up to 2 to 3-fold) at earlier time of infection and different behaviors after 6 weeks when TFF2 keeps increasing, while TFF3 levels is lower." (PMID 29085807, 2017). "For example, Tff3 expression is reduced by the immune system after infection with Citrobacter rodentium, which is not observed in Rag1KO mice." (PMID 35163705, 2022). "pullorum infection significantly elevated (p < 0.05) the renal (CREA, UREA), hepatic (ALT, AST), immunological (IgG, IgM), and inflammatory (TNF-α, IL-6, SAA, CRP) parameters, as well as the expression of trefoil factor 3, Toll-like receptor 2, TNF-α, IL-1β, and IL-6." (PMID 41597538, 2025). "On the other hand, TFF3 is up-regulated upon infection only in TFF1 not expressing cells." (PMID 29085807, 2017). "pdmCA09 infection alone resulted in only slightly increased TFF1 and 2 expression 10 dpi and TFF3 was not upregulated, indicating that extreme induction of TFF1 and 3 is morbillivirus-specific rather than a general response to respiratory virus infections." (PMID 38331906, 2024). "However, there was a significant effect of infection on both TFF2 (F = 3.23 p = 0.015) and TFF3 after transformation (F = 12.04, p <0.0001), but not on IL-33 levels after transformation (F = 1.88 p = 0.1031)." (PMID 34662329, 2021). "Moreover, the presence of TFF1 might influence the regulation of TFF2 and TFF3 expression upon infection, since TFF2 turns to be more induced than expected, while TFF3 is not." (PMID 29085807, 2017).
kidney disease (8 papers, 2015 to 2025). "Urinary TFF-3 levels were associated with death in patients with coexistent kidney disease and predicted all-cause mortality." (PMID 35197070, 2022). "We, therefore, propose that elevations of TFF3 in renal disease might be more revelatory for the cause of restitution than previously thought." (PMID 27066010, 2016). "We also identified genes previously linked to kidney disease, such as fatty acid binding protein 4 (FABP4, log2FC = 5.69), trefoil factor 3 (TFF3, log2FC = 5.58), and angiopoietin 2 (ANGPT2, log2FC = 2.46)." (PMID 40663403, 2025). "The HOXB13 −/TFF3+ subgroup exhibited higher preoperative serum creatinine levels and kidney disease stages than the HOXB13−/TFF3− subgroup, implying a role for TFF3 in kidney function." (PMID 37894380, 2023). "The second origami slip immunosensor structure was used to detect the kidney disease marker Trefoil Factor 3 (TFF3) in human urine." (PMID 34562920, 2021). "Tff3, Vgfa, Vgfb, Vgfc, Il1b and Lgals3 were not differentially expressed in the present study even though they have been implicated in kidney disease." (PMID 26673451, 2015). "TFF3 may be an important molecule for future studies of kidney disease." (PMID 40370722, 2025). "TFF3 as a prognostic biomarker of AKI and CKD needs to fully consider the possible effects of ethnicity, age, sex and the type of kidney disease." (PMID 40370722, 2025).
adenocarcinoma (5 papers, 2008 to 2025). A common cancer characterized by the presence of malignant glandular cells. "Pathologic analysis showed that nearly 60% of Wt mice developed adenocarcinoma; however, none of the Tff3−/− mice developed adenocarcinoma." (PMID 34262017, 2021).
bacterial infection (5 papers, 2017 to 2024). "In this study, we aimed to build on the known role of MUC2 and TFF3 in intestinal bacterial infections and to identify novel regulatory aspects." (PMID 34183045, 2021). "It remains unclear how bacterial count can be relate to reduced TFF3 levels.The most likely explanation is that the bacterial infection induces chronic inflammatory response that in turn inhibits TFF3 geneexpression." (PMID 39917209, 2024).
gastrointestinal disease (4 papers, 2017 to 2024). A disease that occurs in the gastrointestinal system, excluding the hepatobiliary system. "In animal models TFF1 and TFF2, but not TFF3 have been shown to be upregulated during the acute phase of gastrointestinal diseases, while TFF3 reemerged during the restitution phase." (PMID 28355260, 2017). "We also noticed plasma levels of TFF3 showed robust associations with the gastrointestinal domain in PDD and VPD patients, implying that TFF3 could be a high-risk factor for gastrointestinal disease." (PMID 29392081, 2018).
metabolic disorders (4 papers, 2013 to 2025). "Collectively, our results indicate that secreted peptide Tff3 is involved in hepatic glucose homeostasis, providing a promising new lead for developing therapies against the metabolic disorders associated with T2DM." (PMID 24086476, 2013). "Collectively, our results indicated that Tff3 peptides are involved in glucose homeostasis and insulin sensitivity, providing a promising peptide on new therapies against the metabolic disorders associated with T2DM." (PMID 24086476, 2013). "In addition, the comprehensive analysis of genes involved in relevant pathophysiological processes of metabolic disorders, which are also associated with the effect of the Tff3 peptide, was carried out using the qPCR method." (PMID 40426854, 2025). "Given the observed differences in liver lipid accumulation between Tff3−/− and WT animals exposed to a short-term high-fat-diet treatment, we investigated the effects of Tff3 deficiency on genes involved in the development of metabolic disorders, with a focus on MAFLD." (PMID 40426854, 2025). "Metabolic diseases and brain diseases are new directions in TFF3−/− mice research in recent years." (PMID 35039476, 2022). "The same effect was observed following a high-fat diet in knock-out mice, where IL-6 upregulation was associated with a sort of a protective role in the absence of Tff3 when it came to metabolic disorders." (PMID 37108475, 2023).
inflammation (2 papers, 2022). Aberrant reaction of the microcirculation characterized by movement of fluid and leukocytes from the blood into extravascular tissues. "TFF3 is a small peptide that plays an important role in mucosal protection, cell proliferation, and cell migration while the aberrant expression of TFF3 is associated with gastrointestinal inflammation, solid tumors, and other clinical diseases." (PMID 36065350, 2022). "Moreover, colonic inflammation resulted in a decrease of TFF3 and RETNLB expression, indicating a dysfunction in goblet cells." (PMID 35252301, 2022).
intestinal bacterial infections (2 papers, 2017 to 2021). "MUC2 and TFF3 expression undergo changes during intestinal diseases caused by pathogenic bacteria, for instance." (PMID 34183045, 2021).
benign tumors (1 paper, 2024). "As TFF3 is more abundant than the other two proteins (TFF2 is usually undetectable, and TFF1 was significantly more expressed in benign tumors), we mainly focused on TFF3 expression in this study." (PMID 39256888, 2024).
neurodegenerative disease (1 paper, 2018). A disorder of the central nervous system characterized by gradual and progressive loss of neural tissue and neurologic function. "TFF3 levels in patients with PDD/VPD were significantly lower than in the healthy subjects, similar to findings from other neurodegenerative diseases such as AD." (PMID 29392081, 2018).
urological diseases (1 paper, 2013). "The pathological roles of TFF3 in urological diseases remain ill defined." (PMID 24282531, 2013).
TFF3 also shares sentences with these, for which no sentence is quoted: Barrett's esophagus (6 papers); Crohn disease (3); acid reflux (2); cardiac arrest (2); ductal carcinoma in situ (2); gastrointestinal disorders (2); gastrointestinal tumors (2); kidney failure (2); vascular parkinsonism (2); viral infection (2); adenovirus infection (1); Anxiety (1); Brain atrophy (1); Cardiovascular Disease (1); cerebral small vessel disease (1); clear cell carcinoma (1); CNS lymphoma (1); complex endometrial hyperplasia (1); cyst (1); diabetes mellitus type 1 (1); diffuse type adenocarcinoma (1); endometrioid tumor (1); endothelial dysfunction (1); enterocolitis (1); fibrosis (1); gastric adenocarcinoma (1); gastrointestinal carcinomas (1); gingivitis (1); heart disease (1); Hypertension (1).
A further 31 diseases each share a sentence with TFF3 in 1 paper.